MMP9 (matrix metallopeptidase 9)
Diseases named in the same sentence as MMP9 in open-access papers (continued):
Sharing a sentence is not in itself a finding about the gene and the disease.
tumor (continued). "Very interestingly, the expression of tumor-associated genes including vascular endothelial growth factor Vegfa, Il23a, Il23r, and matrix metalloprotease 9 (Mmp9) was almost completely suppressed by the prophylactic administration of ER-464195-01." (PMID 29773794, 2018). "The observed tumor-associated immune responses and the increased metastasis were associated with significantly induced local and systemic levels of MMP-9, VEGF, CHI3L1 and LCN2." (PMID 30111338, 2018). "The reduction in protein production corresponded to a reduced activity of MMP-2 and MMP-9, and demonstrated the “protective function” of Kisspeptin in term of cell change architecture and behavior associated to tumor recurrence." (PMID 29721201, 2018). "Previous studies have indicated that the expression of MMP-2 and MMP-9 are enhanced by radiation in a number of tumor types, and their expressions have been associated with poor prognosis." (PMID 30359388, 2018). "MMP2 and MMP9 expression is associated with tumour cell invasion, and is elevated in various malignancies including HCC." (PMID 29346427, 2018). "Particularly, upregulations of MMP2 and MMP9 are associated with NPC tumor progression and enhance the migration and invasion of NPC cells." (PMID 29416735, 2018). "MMP9 level is associated with the invasive ability of tumor cells and metastasis in xenograft animal models." (PMID 29137391, 2017). "Among the genes amplified was MMP9, encoding a matrix metalloprotease, whose overexpression is associated with tumour progression and invasion." (PMID 28120820, 2017). "There is evidence suggesting that MMP-9 and CD44 associate in mouse and human tumor cells resulting in MMP9 activity localization on the cell surface." (PMID 28326306, 2017). "Recently, several studies have reported that the expression of MMP-9 is associated with migration, invasion, and aggressiveness of tumor cells." (PMID 28187175, 2017). "The high protein expression of Rab1B and MMP9 in 179 CRC tissues is associated with deep tumor invasion, lymph-node metastasis and advanced TNM stage." (PMID 28316326, 2017). "We, and others, have shown that MECs are altered in DCIS and we recently demonstrated that upregulation of the integrin αvβ6 by DCIS-associated MEC confers tumour-promoter activity on MECs through TGF-β-mediated upregulation of MMP-9." (PMID 28330493, 2017). "Yu and Stamenkovic identified a functional relationship between the hyaluronan receptor CD44, MMP9, and transforming growth factor-beta in the control of tumor-associated tissue remodeling." (PMID 28191466, 2017). "Few studies have also been carried out to look for an association between the MMP-9 –1562 C/T polymorphism and the risk of other human tumours." (PMID 28194042, 2017). "In particular, abnormal expression of MMP2 and MMP9 has been frequently detected in solid tumor tissues and is associated with tumor metastasis in many cancer types." (PMID 28114404, 2017). "We have reported that in CAC, attenuation of MMP9 gene was associated with increased susceptibility to tumor incidence and tumor burden compared to WTs." (PMID 27861153, 2017). "We observed that constitutive expression of MMP9 in colonic epithelium is associated with lower tumor incidence, and retained crypt architecture compared to WT littermates, indicating that TgM9 mice were more protected from ulceration in CAC." (PMID 27861153, 2017). "VEGF as well as type IV collagenases MMP2 and MMP9 produced by M2-like TAMs not only promote tumor growth and angiogenesis, but also cause vascular permeability to facilitate tumor migration." (PMID 28467800, 2017). "For instance, gelatinases MMP-2 and MMP-9 are highly associated with tumor progression and both can effectively cleave Fibulin-2." (PMID 28099917, 2017).
tumor (continued). "Combinating the research above with our study, we prompted that M2 macrophages induced MMP9 secretion and promoted tumor aggressiveness and angiogenesis, which is closely associated with the occurrence and progression of Kazakh ESCCs." (PMID 28423526, 2017). "K3 HIF-2α efficiently induces HIF-2 target genes associated with tumor growth and metastasis (MMP9, PAI1, VEGFa, GLUT1) during hypoxia and low glucose stress conditions." (PMID 29281714, 2017). "Neutrophils in particular have been implicated in promoting tumor growth and angiogenesis via the secretion of pro-angiogenic factors including MMP9 and VEGF." (PMID 28764811, 2017). "Tumor-associated neutrophils represent an important source of MMP-9, whose expression in tumor region is increased in non-small-cell lung cancer." (PMID 28589151, 2017). "The impact of MMP-9 (–1562) C/T gene polymorphism on the development of various tumours was analyzed in few studies." (PMID 28194042, 2017). "High expression of MMP-2 and MMP-9 has been often associated to malignant phenotype of many tumor types, with positive correlation with tumor grading and/or staging, thus, they obtained a deep interest as new potential biomarkers." (PMID 27757720, 2017). "Using MMP9 knockout mice, it was found that MMP9 is essential for the migration of smooth muscle and immune cells, and that disruption of MMP9-cell surface interactions can cause a dramatic decrease in cell movement and tumor invasiveness." (PMID 27042827, 2016). "Based on our own data and meta-analysis here, the activity of serum MMP-9 was associated with tumor stage and metastasis status, but its total expression in serum was not related to clinicopathological parameters or survival." (PMID 26918342, 2016). "The angiogenic potential of total MDSCs in tumor-bearing hosts was shown by others to be associated with the production of MMP-9." (PMID 27177328, 2016). "Combined over-expression of MMP9 and loss of E-cadherin membrane positivity in the invasive tumor front (ITF) of OTSCC had a significant association with poorer DFS (Log Rank = 16.040; P value = 0.001)." (PMID 27280700, 2016). "The elevated tumor potential and invasive phenotype was caused by delocalization of aPKC and its activation of Stat3, which was accompanied by elevated MMP-9." (PMID 26872368, 2016). "Among these, matrix metalloproteinase 9 (MMP-9) overexpression has been associated with tumor dissemination." (PMID 27115178, 2016). "sIL-2R was shown to be released from activated T cells mainly due to cleavage by matrix metalloprotease-9 (MMP-9) produced by tumor-associated macrophages." (PMID 27634631, 2016). "MMP-2 and MMP-9 are the two most important proteins associated with tumour cell invasion and metastasis." (PMID 26880967, 2016). "Particularly, abnormal expression of MMP2 and MMP9 is often detected in solider tumor tissues and is associated with tumor metastasis in many cancers including HCC." (PMID 26730736, 2016). "Secondly, the inhibition of miR-29b causes the increasing expression of DNA binding 1 (ID1) and MMP9, which lead to tumor cell invasion." (PMID 27391030, 2016). "We also showed that positive MMP-9 expression in tumor cells was associated with MVD (R = 0.368, p = 0.084); however, it was not statistically significant." (PMID 27429508, 2016). "Tumor spreading is associated with the degradation of extracellular matrix proteins, mediated by the overexpression of matrix metalloproteinase 9 (MMP-9)." (PMID 27115178, 2016). "Among them, MMP-2 (gelatinase-A) and MMP-9 (gelatinase-B) are mostly associated with tumor migration, invasion and metastasis in various cancers." (PMID 27074554, 2016). "It is known that MMPs are critically involved in the processes of tumour cell invasion and metastasis and that MMP-9 is directly associated with angiogenesis and metastatic processes." (PMID 27287498, 2016).
tumor (continued). "MMP-2 and MMP-9 participate in proteolysis of major components of the basement membrane and are associated with tumor invasion and lymph node metastasis." (PMID 27057634, 2016). "There was a significant correlation (χ2 = 10.952; P value = 0.027) between intense MMP9 over expression and loss of membrane positive E-cadherin expression at invasive tumor front." (PMID 27280700, 2016). "Most previous studies have defined the association of tumor MMP-9 expression in NSCLC with a poor survival prognosis, and only a few studies have shown the value of tumor MMP-9 expression for predicting relapse." (PMID 25888323, 2015). "MMP2 and MMP9 expression was statistically associated with a number of tumor features such as location (P=0.002), tumoral differentiation, tumoral stage and tumoral relapse." (PMID 26082904, 2015). "Among these MMPs, the activity of two gelatinases, MMP-2 and MMP-9, was found to be particularly associated with tumor metastasis." (PMID 25625511, 2015). "Log-rank analysis showed a significant association of tumor MMP-9 expression with shortened disease-free survival (p = 0.01) but not with overall survival (p = 0.109)." (PMID 25888323, 2015). "In the BCYW group, MMP-9 expression was significantly associated with tumor size, TNM staging, ER and PR status." (PMID 26656588, 2015). "In particular, MMP-2 and MMP-9 (also known as gelatinase-A and gelatinase-B) are most linked to the malignant phenotype of tumor cells and are commonly used as markers of malignant cancer." (PMID 25922552, 2015). "Direct proof for neutrophils being the major tumor-associated leukocyte type expressing MMP-9 was recently provided in a study employing human xenografts and syngeneic murine tumors." (PMID 26819959, 2015). "Previous studies has shown that binding of SDF-1α to CXCR4 plays a role in tumour metastasis by increasing invasion associated with MMP-9 and MMP-2 activation 20,27,28." (PMID 25753200, 2015). "It has been well documented that CD147 induces the expression of several MMPs, such as MMP-1, MMP-2, MMP-9, which are associated with tumor migration and invasion." (PMID 26507719, 2015). "MMP9-expressing tumor-associated macrophages play a key role in preparing premetastatic sites for eventual malignant cell growth in a manner dependent upon vascular endothelial growth factor receptor-1 (VEGFR-1)." (PMID 26425658, 2015). "Tumor associated macrophages (TAM) also release MMP-9, and the increase in MMP-9 can result in the release of matrix-sequestered vascular endothelial growth factor-A (VEGF-A)." (PMID 25664615, 2015). "Most of these studies applied a scoring system that was based on the extent and intensity of staining for tumor MMP-9 expression and showed that overexpression of tumor MMP-9 was associated with a poor prognosis." (PMID 25888323, 2015). "Previous studies have shown that increased expression of matrix metalloproteinase-2 (MMP-2) and MMP-9 is associated with enhanced tumor invasion and metastasis." (PMID 26021863, 2015). "The overexpression of gelatinases, that is, matrix metalloproteinase MMP2 and MMP9, has been associated with tumor progression, invasion, and metastasis." (PMID 26540114, 2015). "When considering the total population, tumor MMP-9 expression was associated with an increased risk of relapse (p = 0.01) but was not predictive of OS (p = 0.109)." (PMID 25888323, 2015). "Here, we show that MMP9 upregulated in LC, and appeared to be mainly produced by M2 macrophages (tumor-associated macrophages (TAM))." (PMID 25961789, 2015). "Association was found between the MMP-9 polymorphisms and risk of bladder cancer, and tumor stage or grade." (PMID 25352026, 2015). "Traditionally, MMP-9 was associated with tumor angiogenesis and metastasis by lysing proteins of connective tissue." (PMID 24348813, 2014). "Wnt3a expression is associated with the expression of MMP-9 in primary tumor tissue adjacent mesenchymal tissue, and at the metastatic site." (PMID 24564183, 2014).
tumor (continued). "Recent studies revealed that overexpression of MMP-9 in inflammation associated breast cancer, colon cancer, and ovarian cancer led to tumor metastasis." (PMID 25431779, 2014). "In this study, we have demonstrated that an omega-3 PUFAs-rich microenvironment can suppress MMP-9 secretion from CAFs and that this is associated with subsequent tumor hypo-angiogenesis." (PMID 24586907, 2014). "Neutrophil-derived gelatinase B/MMP-9 involvement in tumour-associated intravasation requires neutrophil attraction to the activated endothelial cell surface, neutrophil activation and release of TIMP-1-free gelatinase B/MMP-9." (PMID 24473089, 2014). "MMP-2 interacts with integrins and results in locally-enhanced matrix degradation and elevated MMP-2 and MMP-9 expression is associated with tumor aggressiveness and invasion." (PMID 24959847, 2014). "Tumor size was significantly associated with MMP-9 expression, which was high in tumors larger than 1 cm (P = 0.038)." (PMID 25097794, 2014). "Of the matrix metalloproteinases (MMPs) thought to be involved in cancer, attention has focused on MMP-9 because of its deregulated expression in cancer and its association with tumours’ invasive potential." (PMID 24713998, 2014). "Wnt3a expression in primary tumors was significantly associated with lymph node involvement (p = 0.038) and MMP-9 expression in the primary tumor (p = 0.0387), mesenchyme adjacent to tumor (p = 0.022) and metastatic site (p = 0.004)." (PMID 24564183, 2014). "In summary, it is suggested Kiss-1 inhibits ERK activation and consequently reduces the enzymatic activity of MMP-9 caused by the degradation of NF-κB, which contributes to the suppression of tumour metastasis." (PMID 25260785, 2014). "Gelatinase B/MMP-9 also triggers “the angiogenic switch” by mobilising and activating angiogenic mitogens from matrix stores at the onset of tumour-associated angiogenesis." (PMID 24473089, 2014). "Activation of NF-κB and AP-1 is centrally involved in the induction of the MMP-9 gene associated with the invasion and metastasis of tumor cells by different agents, including TPA and growth factors, such as EGF." (PMID 24433534, 2014). "The chemopreventive effects of CAPE and CAPPE were in part associated with the suppression of the PCNA, FASN and MMP-9 proteins in these tumor-bearing animals." (PMID 24960186, 2014). "Our in vivo data revealed that TM silencing augmented tumor invasiveness, which was associated with increased MMP-9, CD31 and VEGF expression in tumors." (PMID 24886404, 2014). "MMP2 and MMP9 have been frequently detected to be over-expressed in solid tumors and associated with tumor invasion and metastasis." (PMID 25250801, 2014). "MMP2 and MMP9 have been particularly associated with tumor progression, metastatic dissemination, and poor survival in different human cancers, including ccRCC." (PMID 24931473, 2014). "Previous studies had suggested that the expression of MMP-9 was associated with tumor invasion and progression of CRC." (PMID 24960186, 2014). "As is well known, MMP-2 and MMP-9 have been implicated in metastasis and invasion of malignant tumor cells." (PMID 25496480, 2014). "Tumour-associated hypoxia is a major stimulus for angiogenesis and hypoxia exhibits an overall tendency to increase vascular gelatinase B/MMP-9 expression." (PMID 24473089, 2014). "MMP-2 and MMP-9, activated by plasmin, are markers associated with the tumor invasion and metastasis." (PMID 25222667, 2014). "A previous report suggested a role for MMP-9 in tumor invasion relates to the fact that the release of MMP-9 is associated with the metastatic phenotype of transformed rat embryo cells." (PMID 25431779, 2014). "Previous reports have demonstrated that TPA-activated NF-κB and AP-1 activities, and increased MMP-9 expression in response to NF-κB activation, are associated with tumor metastasis." (PMID 24433534, 2014).
tumor (continued). "Particularly, MMP-9 seems to play an important role in tumor vascularization since vessel formation and tumor growth was impaired in the presence of MMP-9-deficient MDSCs." (PMID 24782982, 2014). "Although it is not enough to say that MMP9 is bad prognostic factor, there are still possibility for MMP9 to be associated with tumor invasion because we found the relationship between MMP9 and vascular invasion." (PMID 24504172, 2014). "This investigation intended to evaluate the association between FN-1, ITGA-3, ITGB-5, MMP-2, and MMP-9 gene and protein expression levels in tumor tissue with clinical and histopathological neoplastic parameters of cancer dissemination." (PMID 24737953, 2014). "Gelatinase B/MMP-9 degradation of protease nexin-1 has also been implicated in a novel pathway through which gelatinase B/MMP-9 regulates tumour cell invasion, impairing the capacity of nexin to bind and down-regulate the activity of uPA." (PMID 24473089, 2014). "In assessing a potential association between MMP9 and tumor grade, we found that MMP9 expression was associated with high grade tumors (p= <0.00001)." (PMID 24811362, 2014). "Immunohistochemical (IHC) analysis also revealed that MMP-9 is mainly derived from tumor-associated macrophages (TAMs)." (PMID 24236041, 2013). "It is well recognized that matrix metalloproteinase-9 (MMP9), which is closely associated with tumor invasion and metastasis in several human tumors, can be inhibited by EGFR signaling pathway blockade." (PMID 23496982, 2013). "It is also likely that MMP-9 is produced by the tumor-associated macrophages that are known to be present in PyMT tumors." (PMID 23407024, 2013). "EGFR has been shown to be associated with tumor proliferation and growth, Bcl-2 inhibits tumor apoptosis and MMP-9 and MMP-2 play an indispensable role in tumor invasion and metastasis." (PMID 23420470, 2013). "The plasma levels of lipocalin 2, MMP-9 and the lipocalin 2/MMP-9 complex are associated with more advanced clinical stages and/or tumor sizes in OSCC patients." (PMID 23365550, 2013). "HRS cells produce activated TGFβ1 in primary tumor tissues, predominantly in nodular sclerosing HL, while MMP9 overexpression is associated with adverse clinical outcomes in HL." (PMID 23988031, 2013). "Previous studies of gene expression profile have also revealed that tumor-associated macrophages (TAM) primarily express MMP-9 in DLBCL." (PMID 24236041, 2013). "MMP-9 becomes deregulated during tumorigenesis and is associated with pro-oncogenic events such as neo-angiogenesis, tumor cell proliferation and metastasis." (PMID 23407024, 2013). "Several lines of evidence have shown that p38 activation is required for MMP9 expression, which has been linked to tumor migration and invasion." (PMID 23799978, 2013). "Apart from its key role in tumor invasion, the elevated expression of MMP-9 in different cancers is also implicated in increased tumor progression, including metastasis and shorter survival times." (PMID 23183822, 2012). "Univariate analysis demonstrated that demographic characteristics, behavioural factors, clinical symptoms and raised serum MMP9 concentration were all significantly associated with the presence of neoplasia." (PMID 22433968, 2012). "Categorisation of MMP9 levels into quartiles also demonstrated an association between higher MMP9 levels and neoplasia (χ2=16.7, P=0.001)." (PMID 22433968, 2012). "We demonstrated a significant association between serum MMP9 concentration and the presence of neoplasia." (PMID 22433968, 2012). "Among NF-κB-regulated genes, matrix metalloproteinase (MMP)-9 is closely associated with tumour invasion and tumour-induced angiogenesis, and vascular endothelial growth factor (VEGF) promotes tumour-induced angiogenesis." (PMID 23039130, 2012).